CHRNA6 (cholinergic receptor nicotinic alpha 6 subunit)
Description:
Component of neuronal acetylcholine receptors (nAChRs) that function as pentameric, ligand-gated cation channels with high calcium permeability among other activities. nAChRs are excitatory neurotrasnmitter receptors formed by a collection of nAChR subunits known to mediate synaptic transmission in the nervous system and the neuromuscular junction. Each nAchR subunit confers differential attributes to channel properties, including activation, deactivation and desensitization kinetics, pH sensitivity, cation permeability, and binding to allosteric modulators (Probable). CHRNA6 forms pentameric channels with CHRNB2, CHRNB3 and CHRNA4 that exhibit high sensitivity to ACh and nicotine and are predominantly expressed in only a few brain areas, including dopaminergic neurons, norepirephrine neurons and cells of the visual system. nAChrs containing CHRNA6 subunits mediate endogenous cholinergic modulation of dopamine and gamma-aminobutyric acid (GABA) release in response to nicotine at nerve terminals.
Synonyms: CHNRA6
Tractability: Small molecule: a drug acting on it is in phase 2 or 3 trials; a high-quality ligand is known; it belongs to a druggable protein family. Antibody: its Gene Ontology location is reachable by antibodies, with high confidence; UniProt places it where antibodies can reach, with medium confidence; UniProt predicts a signal peptide or a membrane-spanning region. PROTAC: a small molecule that binds it is known.
Chemical probes: CVN417 (high quality)
Gene: Protein-coding gene on chromosome 8 (42,752,620 to 42,796,392, reverse strand). Ensembl gene ENSG00000147434.
Subcellular location: Synaptic cell membrane
Pathways (Reactome):
Neuronal System: Highly calcium permeable nicotinic acetylcholine receptors; Highly calcium permeable postsynaptic nicotinic acetylcholine receptors
Gene Ontology:
Molecular function: acetylcholine-gated monoatomic cation-selective channel activity; protein binding; acetylcholine receptor activity; neurotransmitter receptor activity; extracellular ligand-gated monoatomic ion channel activity; monoatomic ion channel activity; transmembrane signaling receptor activity
Biological process: acetylcholine receptor signaling pathway; behavioral response to nicotine; calcium ion transport; chemical synaptic transmission; membrane depolarization; monoatomic ion transmembrane transport; neuromuscular synaptic transmission; presynaptic modulation of chemical synaptic transmission; regulation of dopamine secretion; response to acetylcholine; response to nicotine; signal transduction; synaptic transmission, cholinergic; chemical synaptic transmission, postsynaptic; excitatory postsynaptic potential; monoatomic ion transport; regulation of postsynaptic membrane potential
Cellular component: acetylcholine-gated channel complex; dopaminergic synapse; neuron projection; plasma membrane; presynaptic membrane; synapse; synaptic membrane; membrane; postsynaptic membrane
Genetic constraint (gnomAD): Loss-of-function variants: 26 observed, 34.26 expected, observed/expected ratio (o/e) 0.76, 90% interval 0.56 to 1.05. The upper end of that interval is the gene's LOEUF score, 1.05, which puts it in group 4 of 6, group 1 being the genes least tolerant of losing a copy. Missense variants: 481 observed, 546.05 expected, observed/expected ratio (o/e) 0.88, 90% interval 0.82 to 0.95. Synonymous variants: 199 observed, 204.23 expected, observed/expected ratio (o/e) 0.97, 90% interval 0.87 to 1.1.
Homologues: Orthologues: chimpanzee CHRNA6 (100% identical), macaque CHRNA6 (97% identical), dog CHRNA6 (89% identical), guinea pig CHRNA6 (85% identical), mouse Chrna6 (85% identical), rat Chrna6 (84% identical), pig CHRNA6 (84% identical), rabbit CHRNA6 (81% identical), tropical clawed frog chrna6 (70% identical), zebrafish chrna6 (69% identical). Paralogues in human: CHRNA3 (64% identical), CHRNA4 (53% identical), CHRNA2 (52% identical), CHRNB2 (44% identical), CHRNB3 (44% identical), CHRNA1 (43% identical), CHRNA5 (43% identical), CHRNB4 (42% identical), CHRND (35% identical), CHRNA7 (34% identical), CHRNB1 (33% identical), CHRNE (33% identical), and 33 more.
Diseases named in the same sentence as CHRNA6 in open-access papers:
CHRNA6 is named in the same sentence as 20 diseases in open-access papers, as found by Europe PMC text mining. Sharing a sentence is not in itself a finding about the gene and the disease. The quoted sentences say what the papers report.
nicotine dependence (15 papers, 2014 to 2024). Physical and psychological dependence on nicotine. "The clinical implications of the CHRNA6 3-UTR SNP were significantly associated with nicotine addiction and dependence phenotypes." (PMID 38612487, 2024). "Numerous genetic studies have indicated a strong association between the CHRNA6 gene and an increased susceptibility to nicotine addiction and dependence." (PMID 38612487, 2024). "Further, other CHRNA6 SNPs in general show greater nicotine dependence associations in males than females." (PMID 36704741, 2022). "As such, clinical findings provide evidence for the CHRNA6 3′-UTR SNP contributing to the susceptibility of tobacco/nicotine dependence with the strong likelihood of sex-dependent effects." (PMID 36704741, 2022). "The CHRNA6 3′-UTR SNP has been associated with nicotine dependence in males." (PMID 36704741, 2022). "Variations in CHRNA6 are associated with nicotine dependence and tobacco phenotypes." (PMID 25233467, 2014). "We inspected the CHRNA5-CHRNA3-CHRNB4 cluster, the CHRNA6-CHRNB3 cluster and CHRNA4, which are genes showing confirmed association to nicotine dependence and smoking behaviours." (PMID 27957625, 2016). "Hartz and colleagues, focusing on the nicotinic receptor subunit genes associated with nicotine dependence (CHRNA5/CHRNA3/CHRNB4 on chromosome 15q25 and CHRNB3/CHRNA6 on chromosome 8p11) investigated the relationship between nicotine dependence and bipolar disorder." (PMID 35893041, 2022). "We previously undertook pooled sequencing of the coding regions and flanking sequence of the CHRNA5, CHRNA3, CHRNB4, CHRNA6 and CHRNB3 genes and found that rare missense variants at conserved residues in CHRNB4 are associated with reduced risk of nicotine dependence among African Americans." (PMID 24804708, 2014). "Therefore, the objective was to characterize the mediation effects of nicotine dependence on the relationship between genetic variants in the five nicotinic receptor genes (CHRNA5/A3/B4, CHRNB3, and CHRNA6) and lung ADC risk among ever smokers." (PMID 25233467, 2014). "Sex heterogeneity has been observed as a critical factor to be considered with α6 nAChRs, the CHRNA6 gene and the CHRNA6 3′-UTR SNP in nicotine addiction and other neurological diseases." (PMID 36704741, 2022).
dependence (5 papers, 2019 to 2025). "Chrna6 and Slc6a3 have neural functions related to dopamine: Chrna6 is associated with nicotine dependence but also affects the activity of dopaminergic neurons; Slc6a3 encodes the dopamine transporter and is involved in multiple neurological conditions ranging from autism to Parkinson’s disease." (PMID 41226761, 2025). "The authors reported two main findings: the first is that bipolar disorder does not influence and modify the association between nicotine dependence and nicotinic receptor subunit genes, and the second main finding is that variants in CHRNB3/CHRNA6 are independently associated with bipolar disorder." (PMID 35893041, 2022).
Anxiety (2 papers, 2022 to 2024). Intense feelings of nervousness, tension, or panic often arise in response to interpersonal stresses. "In this study, we generated and validated a novel, humanized rodent model to study the effects a human SNP in the 3′-UTR of the CHRNA6 gene in nicotine-induced locomotor activity and anxiety-like behavior." (PMID 35328565, 2022). "We previously demonstrated that a genetic single-nucleotide polymorphism (SNP, rs2304297) in the 3′ untranslated region (UTR) of the human CHRNA6 gene has sex- and genotype-dependent effects on nicotine-induced locomotion, anxiety, and nicotine + cue-induced reinstatement in adolescent rats." (PMID 38612487, 2024). "In sub-chronically treated humanized CHRNA6 3′-UTR SNP rats, significant nicotine effects on locomotion and anxiety-like behavior were sex- and genotype-dependent." (PMID 35328565, 2022). "To test the function of the human CHRNA6 3′-UTR SNP knock-in in vivo, we assessed acute (1-day) and sub-chronic (4-day) nicotine-induced locomotor activity and anxiety-like behavior." (PMID 35328565, 2022). "Following food self-administration, we determined whether the human CHRNA6 3′-UTR SNP knock-in impacts baseline locomotion and anxiety-like behaviors using an open field test, elevated plus maze (EPM), and light/dark box test (LDT)." (PMID 35328565, 2022). "We show the human CHRNA6 3′-UTR SNP knock-in does not affect food reinforcement, locomotor activity, or anxiety." (PMID 35328565, 2022). "Therefore, we hypothesized that the CHRNA6 3′-UTR SNP knock-in would not impact baseline behaviors but G-carrier adolescent rodents would have increased nicotine-induced locomotion and anxiety-like behavior and α6 mRNA expression as compared to C-carrier rodents." (PMID 35328565, 2022).
bipolar disorder (2 papers, 2013 to 2022). A disorder of the brain that causes unusual shifts in mood, energy, activity levels and the ability to carry out day-to-day tasks. "Polymorphisms in CHRNA6 (nicotinic alpha subunit 6 of neuronal cholinergic receptor), have also been reported to be associated with bipolar disorder." (PMID 23326387, 2013).
depression (2 papers, 2020 to 2021). "Consequently, the downregulation of WNT3A, GAGA3, and CHRNA6 may account for the DTMUV-induced depression and neurological symptoms." (PMID 32244328, 2020).
non-small cell lung carcinoma (2 papers, 2020 to 2025). A group of at least three distinct histological types of lung cancer, including non-small cell squamous cell carcinoma, adenocarcinoma, and large cell carcinoma. "The downregulation of CHRNA6 with cancer progression is supported by studies on nicotinic expression in non-small cell lung cancer progression, where expression of CHRNA6 was found higher in non-smokers than smokers." (PMID 41048341, 2025). "Some scholars also concluded that CHRNA9 was similarly overexpressed in HNSC, and the expression of CHRNA6 was significantly higher in molecular features of non-small cell lung cancer." (PMID 33304845, 2020).
breast carcinoma (1 paper, 2024). "Furthermore, the COSMIC database analyzed the mutations of the CACNG4, PKMYT1, EPYC, and CHRNA6 genes in breast cancer." (PMID 38291367, 2024). "The clinico-pathological databases analysis showed that HER2 upregulation and PR downregulation were associated with high CHRNA6 expression, and BRCA1/2 mutation was associated with low CHRNA6 expression, suggesting that CHRNA6 may be a potential diagnostic biomarker in breast cancer." (PMID 38291367, 2024). "We propose that CACNG4, PKMYT1, and CHRNA6 hold promise as potential targets for both the diagnosis and treatment of breast cancer, while EPYC has the potential to be used only as an effective diagnostic biomarker." (PMID 38291367, 2024). "Based on METABRIC database, CACNG4, PKMYT1, and CHRNA6 exhibited differential expression in breast cancer tissues compared to normal tissues." (PMID 38291367, 2024). "Through bioinformatics analysis and qRT-PCR validation, we confirmed the upregulation of CACNG4, PKMYT1, EPYC, and CHRNA6 in breast cancer." (PMID 38291367, 2024). "Based on qRT-PCR analysis conducted on 55 breast cancer patients and normal cases, it was observed that CACNG4, PKMYT1, EPYC, and CHRNA6 mRNA exhibited significantly higher expression levels in breast cancer tissues (BCT) compared to non-tumoral adjacent tissues (NTAT) (P < 0.0001)." (PMID 38291367, 2024).
breast tumors (1 paper, 2024). "Paired t-tests comparing the gene expression profiles of CACNG4, PKMYT1, EPYC, and CHRNA6 between breast tumors and normal tissues revealed an almost 5.55-fold, 2.31-fold, 2.32-fold, and 2.14-fold increase in breast tumors, compared to normal tissues, respectively." (PMID 38291367, 2024). "This study investigates for the first time the mRNA expression of CHRNA6 in breast tumor tissues." (PMID 38291367, 2024).
congenital myasthenic syndrome (1 paper, 2023). Congenital myasthenic syndrome (CMS) is a group of genetic disorders of impaired neuromuscular transmission at the motor endplate characterized by fatigable muscle weakness. "Mutations in CHRNA1 and CHRNA6 have been implicated in fast-channel congenital myasthenic syndrome (MIM#608930) characterized by early-onset progressive muscle weakness and chronic pain." (PMID 36375841, 2023).
esophageal squamous cell carcinoma (1 paper, 2021). Esophageal squamous cell carcinoma (ESCC) is a type of esophageal carcinoma (EC) that can affect any part of the esophagus, but is usually located in the upper or middle third. "Epidemiological studies have shown that CHRNA6 mutations can increase the susceptibility to esophageal squamous cell carcinoma." (PMID 34912722, 2021).
viral infection (1 paper, 2019). "Some proximal genes targeted by these 6 REs (FSCN1, GSTP1, JAM3, CHRNA6, NFAT5, and PRRC2A) are related to immune response, viral infection, and/or HCC based on ontological analysis." (PMID 31639042, 2019).
cancer (4 papers, 2020 to 2025). A tumor composed of atypical neoplastic, often pleomorphic cells that invade other tissues. "Besides, the Venn diagram demonstrated that there were three mutual DEGs in all three cancers: CHRNB4, CHRNA9, and CHRNA6." (PMID 33304845, 2020). "However, there is currently no in silico or experimental study on the effects of the CHRNA6 gene on cell proliferation and tumor progression, and it could be a potential novel biomarker in cancer studies." (PMID 38291367, 2024).
tumor (4 papers, 2014 to 2024). "In particular, the expression of the CHRM1, CHRNA2, CHRNA4, CHRNA6, CHRNA7, and CHRNB2 genes was increased in samples from the tissue of the anterior edge of the tumor." (PMID 38393158, 2024). "In our study, we identified three upregulated genes (CHRNB4, CHRNA6, and CHRNA9) of the whole CHRNs between tumor tissues and normal controls in three kinds of SCCs." (PMID 33304845, 2020). "In normal kidney tissue ANKS1B, ACOT6, EYS, CHRNA6, MT1G and UTY were up regulated in smokers in comparison to non-smokers; however, these genes tended to be down regulated in smokers versus non-smokers in ccRCC tumor tissue." (PMID 24479813, 2014).
CHRNA6 also shares sentences with these, for which no sentence is quoted: lung carcinoma (3 papers); Parkinson disease (2); autism (1); glaucoma (1); neurodevelopmental disorder (1); neurological diseases (1); schizophrenia (1).